KRTAP19-6 (keratin associated protein 19-6)
Description:
In the hair cortex, hair keratin intermediate filaments are embedded in an interfilamentous matrix, consisting of hair keratin-associated proteins (KRTAP), which are essential for the formation of a rigid and resistant hair shaft through their extensive disulfide bond cross-linking with abundant cysteine residues of hair keratins. The matrix proteins include the high-sulfur and high-glycine-tyrosine keratins.
Synonyms: KAP19.6
Tractability: No criterion of Open Targets' tractability assessment is met for any kind of drug.
Gene: Protein-coding gene on chromosome 21 (30,541,535 to 30,541,864, reverse strand). Ensembl gene ENSG00000186925.
Pathways (Reactome):
Developmental Biology: Keratinization
Gene Ontology:
Molecular function: protein binding
Cellular component: cytosol
Genetic constraint (gnomAD): Loss-of-function variants: 0 observed, 0.99 expected, observed/expected ratio (o/e) 0, 90% interval 0 to 1.73. That is too few expected variants to judge how well the gene tolerates losing a copy. Missense variants: 69 observed, 73.97 expected, observed/expected ratio (o/e) 0.93, 90% interval 0.77 to 1.14. Synonymous variants: 20 observed, 28.79 expected, observed/expected ratio (o/e) 0.69, 90% interval 0.49 to 1.01.
Homologues: Orthologues: rabbit KRTAP19-6 (60% identical), pig KRTAP19-6 (59% identical).